MPST (mercaptopyruvate sulfurtransferase)
Diseases named in the same sentence as MPST in open-access papers (continued):
Sharing a sentence is not in itself a finding about the gene and the disease.
uterine corpus endometrial carcinoma (1 paper, 2025). A endometrial carcinoma (disease) that involves the body of uterus. "Based on these findings, SLC2A1 and MPST may serve as diagnostic markers for uterine corpus endometrial carcinoma (UCEC)." (PMID 40746529, 2025). "Furthermore, research has shown that MPST is present in endometrial tumors, indicating a direct connection to the survival rate of patients diagnosed with uterine corpus endometrial carcinoma." (PMID 40746529, 2025). "However, the specific roles of SLC2A1 and MPST in tumor immune cell infiltration, abnormal DNA methylation, and prognosis in uterine corpus endometrial carcinoma (UCEC) have not yet been elucidated." (PMID 40746529, 2025).
cancer (17 papers, 2015 to 2025). A tumor composed of atypical neoplastic, often pleomorphic cells that invade other tissues. "In our study, we detected a significant overexpression of SLC2A1 in 22 out of 33 human cancer tissues, while MPST was upregulated in 13 out of 33 tumor tissues." (PMID 40746529, 2025). "We analyzed the expression levels of the SLC2A1 and MPST genes using cancer datasets from the TCGA database." (PMID 40746529, 2025). "In summary, this study investigated the expression of SLC2A1 and MPST across different cancer types." (PMID 40746529, 2025). "The protein level of MPST, found to be significantly upregulated in a variety of cancers, serves multiple complex roles, profoundly influencing cancer cell growth, proliferation, and resistance to oxidative stress." (PMID 39062461, 2024). "Cystathionine β-synthase (CBS), CSE (cystathionine γ-lyase) and 3-mercaptopyruvate sulfurtransferase (3-MST) have emerged as three significant sources of hydrogen sulfide (H2S) in various forms of mammalian cancer." (PMID 36978895, 2023). "Although the role of MST in cancer is evident in the control of metabolic reliance, cell survival, and proliferation, MPST expression regulation upon carcinogenesis and its fitness into the progressive cancer phenotype is not often explored." (PMID 32882966, 2020). "Augsburger and Szabo announced that the MPST/H2S system is involved in supporting cancer cell proliferation, as well as suggested a potential regulatory role in bioenergetics and cell-signaling functions." (PMID 32041330, 2020). "While the role of MPST (also known as 3-MST) in PanNETs is unclear, there is growing evidence that hydrogen sulfide producing enzymes like MPST are more abundant in numerous cancers and may serve as druggable targets." (PMID 40217502, 2025). "Both SLC2A1 and MPST have been identified as important regulators in cancer." (PMID 40746529, 2025). "In this study, we investigate the expression of SLC2A1 and MPST across various types of cancer." (PMID 40746529, 2025). "The potential role of MPST in cancer cells was recently discussed by Augsburger and Szabo." (PMID 32041330, 2020). "Thus, SLC2A1 may influence UCEC progression by modulating cancer cell metabolism, and there may be a connection between MPST and UCEC development due to its role in cysteine and methionine metabolism." (PMID 40746529, 2025). "In recent years, our research investigations have focused on the presence and role of enzymes (MPST, CTH, CBS) involved in the metabolism of low-molecular-weight sulfur compounds and H2S in normal and/or cancer cells." (PMID 38397425, 2024). "In the present study, the increased H2S and thiosulfate levels in HBITC-treated SH-SY5Y cells have been associated with downregulation of the level of rhodanese and MPST, but the level of γ-cystathionase has not been changed in both cancer cell lines." (PMID 29508061, 2018). "Therefore, the exact role of MPST in cancer development remains still not elucidated, and could be a worthy investigating area and topic to open the discussion for the future." (PMID 32041330, 2020).
tumor (9 papers, 2018 to 2025). "Immunohistochemical staining data from the HPA database further confirmed the higher expression of SLC2A1 and MPST in tumor tissues compared to adjacent normal endometrial tissues." (PMID 40746529, 2025). "CBS, CSE, and MPST are differently expressed in various tissues and organs, but their levels can also be up or downregulated under diverse conditions and in different tumor types." (PMID 37483514, 2023). "Following this blueprint led to circumscribing the overall metabolic characteristics of motile cells across thirty patients’ GB, and to identifying MPST as a metabolic enzyme crucial for GB cell motility and tumor development." (PMID 36310164, 2022). "Discovery of the participation of MPST in the control of GB cell motility was made possible by considering metabolism in the context of its cell-by-cell variability in the human tumor." (PMID 36310164, 2022). "Alteration of GB cell properties by MPST knockdown translates in vivo into reduced tumor burden, and a robust increase in mice survival, albeit the cells retain their tumor-initiating properties." (PMID 36310164, 2022). "Functional assays with patients’ tumor-derived cells and -tissue organoids, and genetic and pharmacological manipulations confirmed that the cells depend on enhanced ROS production and MPST activity for their motility." (PMID 36310164, 2022). "With TCGA cohort, we studied endogenous H2S synthetase expressions and, found that CSE/CTH, CBS and MPST expressions were enhanced in tumor tissues comparing with normal samples." (PMID 32195181, 2020). "We compared the methylation values of SLC2A1 and MPST between normal and tumor tissues." (PMID 40746529, 2025). "Finally, we evaluated the consequences of MPST knockdown on overall tumor burden using brain xenografts of PDC stably expressing luciferase and either shControl or shMPST." (PMID 36310164, 2022). "Specifically, SLC2A1 is overexpressed in the tumor tissues of UCEC patients, and MPST also exhibits a high level of expression in these tissues." (PMID 40746529, 2025). "In ccRCC, we observed increase in MPST expression in one tumor, no change in 7 tumors and 2.2–9.0-fold decrease in 15 tumors." (PMID 29793450, 2018). "Correlation analysis indicated that MPST expression levels differed significantly according to clinical stage, histological type, histological grade, and age, but not according to tumor remnant size." (PMID 40746529, 2025). "Furthermore, there is no sufficient data regarding MPST functions in the MCF-7 cell line, and the information to determine the MPST role in the tumor process." (PMID 32041330, 2020).
infection (4 papers, 2018 to 2023). The state of being infected such as from the introduction of a foreign agent such as serum, vaccine, antigenic substance or organism. "MPST protein levels were also increased in both WT and CSE−/− macrophages after infection; however, the transcription of MPST decreased after infection." (PMID 32139610, 2020).
adenocarcinoma (1 paper, 2024). A common cancer characterized by the presence of malignant glandular cells. "Our studies provided new information about the increase in MPST enzyme expression in response to S-allyl-L-cysteine in the adenocarcinoma in vitro cellular model for both the investigated cell lines." (PMID 38397425, 2024). "In our research model, we confirmed the antiproliferative potential of SAC and concluded that our studies provided current information about the increase in MPST gene expression mediated by S-allyl-L-cysteine in the adenocarcinoma in vitro cellular model for the MCF-7 and MDA-MB-231 cell lines." (PMID 38397425, 2024).
cardiovascular disease (1 paper, 2023). "Hyperhomocysteinemia is a well-known risk factor for cardiovascular disease and leads to downregulation of CBS, CSE, and 3-mercaptopyruvate sulfurtransferase (3-MST) in the kidneys and liver, resulting in decreased H2S plasma levels." (PMID 36977089, 2023).
heart disease (1 paper, 2021). "This study is the first to investigate the cardiovascular phenotype in MPST KO mice and further studies should aim to extend understanding in the role and pathophysiology of MPST in the onset of age-related heart disease." (PMID 34613340, 2021).
neurodegenerative disease (1 paper, 2023). A disorder of the central nervous system characterized by gradual and progressive loss of neural tissue and neurologic function. "However, a decrease in the expression of H2S producing enzyme (primarily CSE, but also CBS and MPST) and consequently the loss of persulfidation were found in aging and different age-induced diseases, such as neurodegenerative diseases." (PMID 37288744, 2023).
MPST also shares sentences with these, for which no sentence is quoted: glioblastoma (4 papers); astrocytoma (3); neuroblastoma (3); brain cancer (2); lung carcinoma (2); Anxiety (1); benign tumors (1); brain disease (1); cardiac hypertrophy (1); contact dermatitis (1); E. coli infection (1); head and neck squamous cell carcinoma (1); heart failure (1); hepatocellular carcinoma (1); inflammatory bowel disease (1); liver cancer (1); mental disorder (1); mental retardation (1); mesothelioma (1); neurological disorders (1); neuropathy (1); Obesity (1); oncocytoma (1); renal cell carcinoma (1); triple-negative breast carcinoma (1); urothelial carcinoma (1).